CCND1 (cyclin D1)
Diseases named in the same sentence as CCND1 in open-access papers (continued):
Sharing a sentence is not in itself a finding about the gene and the disease.
tumor (continued). "This interaction is requisite for K9 histone H3 acetylation, and such PKM2‐dependent chromatin modifications bear significant implications for brain carcinogenesis, tumor cell proliferation, cell cycle dynamics, and EGF‐mediated expression of cyclin D1 and c‐Myc." (PMID 38034101, 2023). "The cyclin D1 expression in SIACs has not yet been comprehensively studied, owing to the rarity of this tumor." (PMID 37894399, 2023). "STAT3 had been found to be over-activated and played a tumor-promoting role in a variety of human cancers because STAT3 could act as a transcription factor to promote the expression of cyclin-B1, cyclin-D1, MMP2, MMP9 and other pro-tumor proteins." (PMID 37161425, 2023). "The results showed that the expression levels of p-β-catenin, β-catenin, and CCND1 proteins were significantly increased in tumor tissues overexpressing CAMKK2, while the expression levels of p-β-catenin, β-catenin, and CCND1 proteins were decreased in the bufalin-treated group." (PMID 38082327, 2023). "EC mice exposed to combined treatment of CuNPs and radiation showed a marked reduction in tumor volume, ALT and CAT, creatinine, calcium, and GSH, along with elevation in MDA, caspase-3 in parallel with inhibition of NF-κB, p38 MAPK, and cyclin D1 gene expression." (PMID 36905557, 2023). "Indeed, the upregulation of 37 different MYC-regulated genes including BCL2, CCND1, PCNA, PGK1, and VEGFA, all promote tumor formation." (PMID 36831657, 2023). "In addition, we detected a decrease in CENPA lactylation level and downstream genes protein level (such as YY1, CCND1 and NRP2), in 2-DG treated HCC tumor tissues." (PMID 37928273, 2023). "KAT2A was highly expressed in non-small-cell radiation-induced lung cancer and may promote tumor progression by upregulating E2F1 and cyclin d1." (PMID 38058677, 2023). "STAT3, which may be a key target of miR-124, upregulates the expression of cyclin D1, survivin, Bcl-xL, and vascular endothelial growth factor (VEGF), which suppress cell apoptosis and promote tumor growth." (PMID 36821071, 2023). "The relationship between cyclin D1 and the degree of tumor differentiation is controversial and has not yet been clarified." (PMID 36982894, 2023). "On the other hand, immunohistochemical staining showed that the expression of tumor progression markers such as N-cadherin, Vimentin, VEGF, Ki67, and Cyclin D1 was decreased along with the downregulation of VIRMA, except E-cadherin exhibited a contrary tendency." (PMID 36691046, 2023). "In the MELF area, the expressions of cyclin D1 and p16 were strong but sometimes absent in the contiguous or adjacent conventional tumor area." (PMID 38002025, 2023). "With the high abundance of Cyclin D1 and CDK4/6, cells could escape from critical cell checkpoints, then grow out of control and develop into malignant tumor cells." (PMID 37814227, 2023). "Thus, the exclusion ZWINT intron in the tumour samples is predicted to lead to higher levels of total ZWINT expression, consequent elevation of cyclin D1 and E1 and cyclin dependent kinase 4 expression and promotion of cell proliferation." (PMID 37924098, 2023). "Wnt ligands accelerate tumor proliferation in NSCLC, partly by upregulating Myc and CCND1." (PMID 37841927, 2023). "PTHrP ablation leads to a significant decrease in tumor growth and metastasis as well as the reduced expression of several factors known to support tumor progression, including: CXCR4, Ki67, Bcl-2, AKT1, and Cyclin D1." (PMID 38435029, 2023). "Given the multiple contexts that may be found in the highly heterogeneous tumor environment, a better understanding of CCNI regulation will be critical to unveil the full significance of the CCNI and CCND1 interplay." (PMID 37081792, 2023). "Recent study revealed that NSG1 might participate in the tumor occurrence and development by influencing the JAK/STAT signaling pathway and cyclin D1, whereas the role of NSG1 on ESCC development remains to be uncovered." (PMID 37872157, 2023).
tumor (continued). "Then we injected the stable cell lines containing m3E sgRNAs for CBX8, CCND1, PTP4A3, RPS6KA5 and TNFSF10 into nude mice and checked whether tumor growth was repressed." (PMID 38012744, 2023). "Moreover, TAX evidently inhibited the tumor growth in nude mice and the expression of c-Myc, cyclin D1, p-AKT and FGFR2 were down-regulated in xenograft tumor." (PMID 37567936, 2023). "Despite profound gliosis in the tumor vicinity, there were very few MIB1+ and CCND1+ cells." (PMID 38066208, 2023). "By downregulating cyclin D1, inhibiting MMP-2 secretion, and activating the ERK1/2 and apoptosis signaling pathways, inhibition of COMMD7 may reduce tumor growth and invasion." (PMID 36776284, 2023). "In the tumor xenografts, immunohistochemistry staining demonstrated that TAX treatment decreased the number of Ki67-positive cells and reduced the expression of c-Myc, cyclin D1, p-AKT and FGFR2." (PMID 37567936, 2023). "In addition, the GSCALite database was explored based on the tumor treatment response portal (CTRP) and GDSC to assess the correlation of drug sensitivity with CCND1 and MYO1B." (PMID 37481637, 2023). "The application of this compound hindered tumor development and decreased the production of phosphorylated LPR6, phosphorylate and unphosphorylated DVL2, Ser9 phosphorylated GSK3β, active β-catenin, and cyclin D1." (PMID 35509712, 2022). "VIP/VIPR1 signaling maintained tumor proliferation and invasiveness by upregulating the expression of cyclins and angiogenic factors, including cyclin D1, MMP-2/MMP-9, VEGF, and COX-2, as well as stimulating tumor growth through the activation of PKA/ERK1/2 pathway." (PMID 35864952, 2022). "Similarly to cyclin D1, ERK1/2 is considered a proto-oncogene that drives tumor cell proliferation, epithelial–mesenchymal transition (EMT), migration, and invasion." (PMID 36077614, 2022). "In vivo, β-catenin, Cyclin D1 and Mmp7 clearly designated tumor from normal colon; however, no downregulation of Wnt/β-catenin targets was observed with dietary SPI intake." (PMID 35159382, 2022). "Notably, cyclin D1 is a downstream effector of the PI3K/AKT pathway, one of the critical pathways that promote tumour development." (PMID 35668070, 2022). "The majority of cases (27/32; 84.4%) showed positive staining for cyclin D1 at the front of invasion whereas the center of the tumor was negative." (PMID 34495397, 2022). "On Cox regression model analysis, various factors, such as gender, age, tumor type, tumor location, tumor diameter, histological grade, lymph node metastasis, depth of invasion, pTNM stage, VM, SOX17 expression, Cyclin D1 expression, and VE-cadherin expression, were identified as prognostic factors." (PMID 36072972, 2022). "Moreover, associations between the expression of several genes or proteins and the benefits of paclitaxel, such as CCND1, ABCB1, BCL-2, and SPARC in different tumor types, have been reported in multiple studies 25–29." (PMID 35595817, 2022). "After PSM, tumor stage and histologic classification were well balanced between the cyclin D1-negative and -positive groups." (PMID 35723316, 2022). "When complexes loaded with both DOX and siSTAT3 were exposed to ultrasound, the treatment significantly decreased expression of pro-tumor and pro-mitotic factors STAT3, Cyclin D1, and c-Myc, reduced cell viability, and inhibited tumor growth, indicating efficacy for cancer therapy." (PMID 36365214, 2022).
tumor (continued). "While one case was completely negative for cyclin D1, positive staining was observed an average of 48.7% of positive stained tumor cells in all other cases." (PMID 34495397, 2022). "GAL1R blocked the proliferation of tumor cells through the activation of ERK1/2 and cyclin-dependent kinase inhibitors, leading to cell-cycle arrest (regulating cell cycle control proteins such as cyclin D1, p57, p27)." (PMID 35954419, 2022). "The expression levels of CCND1, VEGFA, AURKB, HDAC1, HSP90AA1, and HSP90AB1 were positively correlated with immune cell infiltration levels, whereas the expression levels of SIRT2 and CASP9 were negatively correlated with the tumor purity of BRCA." (PMID 35845599, 2022). "However, the silencing of VE-cadherin expression significantly inhibits Cyclin D1 expression and enhances SOX17 expression, which can inhibit tumor progression." (PMID 36072972, 2022). "Moreover, the re-expression of GAL1R in GAL1R/GAL2R-negative HNSCC cells also suppressed tumor cell proliferation through ERK1/2-mediated actions on cyclin-dependent kinase inhibitors and cyclin D1." (PMID 35954419, 2022). "Besides, the protein levels of FOXK1, β‐catenin, cyclin D1, and c‐Myc were downregulated in shRNASEH1‐AS1‐transfected tumor xenografts." (PMID 35166053, 2022). "We observed non-significant difference in tumor mRNA levels of cyclin D1 and lower levels of cyclin E in doxorubicin-treated mice than in controls." (PMID 36483592, 2022). "The mRNA expression of CCND1 and CYP2S1 genes was high in COAD tumor tissues, while the mRNA expression of GSTM1 gene was low in COAD tumor tissues, and the difference was statistically significant, which was consistent with the previous results of TCGA database and GEPIA2 data analysis." (PMID 36203457, 2022). "In addition to these proinflammatory factors, we also analyzed the expression of tumor proliferation-related proteins (PCNA and cyclin D1)." (PMID 33558702, 2022). "CCND1 is an important cell cycle regulatory protein that promotes the proliferation of cancer cells by forming a cell cycle-dependent complex with cyclin-dependent kinase 4 (CDK4), which contributes to the development of many tumor diseases, including HCC." (PMID 35873910, 2022). "Activated CTNNB1, through signalling events initiated by phosphorylation of AKT, translocates to the nucleus and initiates the expression of downstream targets such as CCND1 and CCNE, TWIST, SNAIL, MMPs, C-MYC, and several others rendering tumor cells more invasive." (PMID 33758996, 2022). "Immunohistochemistry analysis of mouse subcutaneous tumor showed decreased expression of nuclear EGFR targets (cyclin D1, Aurora A, B-myb, c-Myc) in the absence of NONO, indicating that NONO was closely related to the nuclear EGFR transcription network." (PMID 35013116, 2022). "In a retrospective study carried out at four French institutions, patients with recurrent and/or metastatic HNSCC experienced accelerated tumor growth and had shorter PFS after anti-PD-1 and anti-PD-L1 treatment, with three of the patients harboring a CCND1 amplification." (PMID 35371031, 2022). "Tumor cells within the lymph node metastases showed positive staining for e-cadherin in 75% and for cyclin D1 in 49% of the cells but were negative for vimentin in 13 out of 16 cases (81.3%)." (PMID 34495397, 2022). "Given the imbalance in tumor stages among the basic characteristics of patients the between cyclin D1-positive and -negative groups, survival was reassessed between these two groups in the PSM cohort." (PMID 35723316, 2022). "Previous study has suggested the proto-oncogenic roles of FOXM1 and its downstream target genes Cyclin D1, Survivin and CDC25B in tumors, which include facilitating cell cycle progression and inducing tumor cell proliferation, as well as its relation with the poor prognosis of cancer patients." (PMID 35624501, 2022).
tumor (continued). "We also examined the protein level of tumor tissues in two groups, which showed that PHGDH and pathway-related indicators β-catenin, c-myc, cyclin D1, PCNA, Bcl2, N-cadherin, vimentin, and Snail expression level were lower and BAX and E-cadherin higher in CBR-5884 group." (PMID 36105480, 2022). "Additionally, IHC staining showed decreased expression of Ki-67, cyclin D1, cyclin E1, and E2F1 in sh-CENPU-treated Huh-7 xenograft tumours." (PMID 35844791, 2022). "Altogether, these results confirmed that the CHREBP/cyclin D1 axis could regulate GC progression via the Rb/E2F1 pathway, the activation of which has been elaborated to promote G1/S transition and enhance tumor cells proliferation." (PMID 35768405, 2022). "Our preliminary deep sequencing data also showed that CASC15 was upregulated in LSCC and positively correlated with cyclin D1 (data not shown), which mediates cell cycle progression and has critical roles in tumor growth." (PMID 35216636, 2022). "Moreover, consistent with the in vitro data, western blot analysis revealed that the effects of ESCCAL-1 overexpression on cell cycle regulators (CDK4, CCND1, and CDKN1A) were partially abolished by knockdown of Gal-1 in ESCC tumor tissues." (PMID 35233069, 2022). "Likewise, the expression of cyclin D1 and CYR61 in tumor tissues was markedly reduced, as examined by immunohistochemistry analysis and Western blotting, respectively." (PMID 36358761, 2022). "MYC and CCND1 are well known WNT-induced genes that promote cell proliferation and tumor growth." (PMID 35908024, 2022). "Notably, reversible mitochondrial inhibition yielded durable suppression of tumor proliferation, migration, and invasion via the PI3K/Akt/FoxO1/Cyclin D1 pathway." (PMID 35865479, 2022). "Furthermore, we also confirmed the regulatory effects of cNFIB on CCND1, MMP1, VEGFA, and FOS expression, the key downstream targets of ERK signaling responsible for tumor proliferation and metastasis." (PMID 35039066, 2022). "Moreover, raddeanin A efficiently inhibited tumor growth in a xenograft mouse model by reducing the expression of the β-catenin protein and the Wnt-target genes CCND1 (Cyclin D1) and MYC (c-myc) with 2.5 and 5 mg/kg." (PMID 35053565, 2022). "Abnormal activation of the Wnt/β-catenin pathway has been found to play an important role in the occurrence and development of tumors, and its pathway-related factors cyclin D1, c-jun, CD44, and c-Met are considered to be effective oncogenes in tumor progression." (PMID 34426559, 2021). "In addition, IHC staining showed that METTL3 depletion increased APC expression with corresponding decreased expression of β-catenin, cyclin D1, c-Myc and PKM2 in tumour tissues." (PMID 34155197, 2021). "Crocin could induce apoptosis in tumor cells by down-regulating the expression of Bcl-2, survivin, cyclin D1, and up-regulating the expression of Bax in BALB/c xenograft tumor." (PMID 34648579, 2021). "Almost all EMPD samples (108/110, 98.2%) were positive for CDK4 staining (staining was defined as positive when at least some of the tumor cells were stained), and 98 of 110 (89.1%) EMPD samples were positive for cyclin D1 staining at various staining intensities." (PMID 34395284, 2021).
tumor (continued). "A DMR was also identified in the BCL9L gene—an activator of Wnt signaling associated with B cell malignancies that have been implicated in cancer development and epithelial-mesenchymal transition through a down-regulation of c-Myc, cyclin D1, CD44, and vascular growth factor in tumor cells." (PMID 34502260, 2021). "In PAs, the correlation between cyclin D1 expression with Ki67 and tumor size has been reported, and nuclear accumulation of β-catenin and over expression of cyclin D1 and c-Myc was found in non-functioning PA." (PMID 33671384, 2021). "Despite reductions in both c-myc and cyclin D1 gene expression, Ki67 tumor staining did not change, demonstrating that these tumor cells are actively dividing." (PMID 34073112, 2021). "Furthermore, an in vivo tumor xenograft experiment showed that tumor initiation is potentially delayed in CAMSAP3 knockout tumors with the downregulation of p‐ERK and cyclin D1, resulting in a senescence‐like phenotype." (PMID 34724356, 2021). "Our data demonstrated that overexpression of FHL1 inhibited the proliferation, colony formation potential, and expression of CdK4 and Cyclin D1, whereas ablating FHL1 promoted their proliferation and colony formation potential, suggesting that FHL1 acts as a tumor suppressor in CRC." (PMID 34335951, 2021). "As a result, increases of oncogene cyclin D1 and EMT markers can lead to tumor progression." (PMID 34204169, 2021). "Consistently, qPCR analysis of RNA from carcinoma or non-tumour liver from PI3Kγ-/- mice or WT mice kept on a HFD indicates that PI3Kγ ablation reduced the abundance of cyclin D1 mRNA in HCC but not in non-tumour liver." (PMID 34704005, 2021). "Likewise, formation and growth of U87MG multi‐cellular tumour spheroids in lower (2% compared to 10%) FCS resulted in a similar decrease in Rb S807/811 phosphorylation, total Rb and cyclin D1 protein and an increase in DYRK1B and p27 expression." (PMID 34708541, 2021). "Protein–protein interaction of the gene in the ceRNA networks shown that the high-scoring proteins were obtained including CD44, MYC, CCND1, ESR1, IL6, and VEGFA, which suggesting that they might jointly regulate the occurrence and development of tumor." (PMID 34655361, 2021). "In addition, the HPA data of CCND1, PLK1, and CD44 expression in tumor smaples exhibited high staining intensities, and all the IHC images were obtained from the HPA database to validate the expression of genes in the cancer types at the protein level." (PMID 34063946, 2021). "The two sampling methods yielded the same cyclin D1 expression status (positive or negative) in 24 of the 26 tumours." (PMID 34041255, 2021). "In this study, the differential expression analysis showed that among all cyclin family members, there were six significant DEGs (CCNA2, CCNB1, CCND1, CCNE1, CCNF, and CCNJL), five of which were overexpressed in tumor samples compared to normal controls, while CCNJL was downregulated." (PMID 33996604, 2021). "The anticancer effects of AA on HCC were predicted to be associated with regulating tumor cell proliferation, apoptosis, angiogenesis, tumor invasion, and metastasis via various pathways such as EGFR signaling pathway, ESR1 signaling pathway, and CCND1 signaling pathway." (PMID 33688369, 2021). "In the present study, MALAT1 upregulation in EOC cells was correlated with significantly higher levels of p-PI3K, p-AKT, cyclin D1, vimentin, YAP, and ZEB2, combined with a reduction of E-cadherin expression, thus promoting tumor cell proliferation and metastasis." (PMID 34638541, 2021). "In addition, we detected the expression levels of three tumor-specific biomarkers, namely, CD9, MCT1, and cyclin D1, in exosomes." (PMID 34336125, 2021). "Up‐regulated CCND1 and CCND2 expression are related to tumor metastasis." (PMID 33473276, 2021).